ENSG00000263620 (novel protein)
Gene: Protein-coding gene on chromosome 17 (8,150,816 to 8,162,975, reverse strand). Ensembl gene ENSG00000263620.
Genetic constraint (gnomAD): Loss-of-function variants: 0 observed, 15.43 expected, observed/expected ratio (o/e) 0, 90% interval 0 to 0.19. Missense variants: 92 observed, 149.58 expected, observed/expected ratio (o/e) 0.62, 90% interval 0.52 to 0.73. Synonymous variants: 64 observed, 59.83 expected, observed/expected ratio (o/e) 1.07, 90% interval 0.87 to 1.32.